ELAVL1 (ELAV like RNA binding protein 1)
Description:
RNA-binding protein that binds to the 3'-UTR region of mRNAs and increases their stability. Involved in embryonic stem cell (ESC) differentiation: preferentially binds mRNAs that are not methylated by N6-methyladenosine (m6A), stabilizing them, promoting ESC differentiation (By similarity). Has also been shown to be capable of binding to m6A-containing mRNAs and contributes to MYC stability by binding to m6A-containing MYC mRNAs. Binds to poly-U elements and AU-rich elements (AREs) in the 3'-UTR of target mRNAs. Binds avidly to the AU-rich element in FOS and IL3/interleukin-3 mRNAs. In the case of the FOS AU-rich element, binds to a core element of 27 nucleotides that contain AUUUA, AUUUUA, and AUUUUUA motifs. Binds preferentially to the 5'-UUUU[AG]UUU-3' motif in vitro. May also bind with ZNF385A the CCNB1 mRNA (By similarity). Increases the stability of the leptin mRNA harboring an AU-rich element (ARE) in its 3' UTR.
Synonyms: HuR; Hua; MelG; ELAV1
Tractability: Small molecule: a high-quality ligand is known; it belongs to a druggable protein family. PROTAC: UniProt records ubiquitination sites on it; ubiquitination databases record sites on it; its protein half-life has been measured; a small molecule that binds it is known.
Chemical probes: CMLD-2
Gene: Protein-coding gene on chromosome 19 (7,958,573 to 8,006,062, reverse strand). Ensembl gene ENSG00000066044.
Subcellular location: Cytoplasm; Nucleus; Cytoplasm, Stress granule; Cytoplasm, P-body
Subcellular location (Human Protein Atlas): Nucleoplasm; Cytosol; Nucleoli
Pathways (Reactome):
Disease: Dengue Virus-Host Interactions
Metabolism of RNA: HuR (ELAVL1) binds and stabilizes mRNA
Gene Ontology:
Molecular function: double-stranded RNA binding; miRNA binding; mRNA 3'-UTR AU-rich region binding; mRNA 3'-UTR binding; protein binding; protein homodimerization activity; protein kinase binding; RNA binding; mRNA binding; protein-RNA adaptor activity; lncRNA binding; nucleic acid binding
Biological process: 3'-UTR-mediated mRNA stabilization; mRNA stabilization; negative regulation of miRNA-mediated gene silencing; positive regulation of translation; protein homooligomerization; regulation of stem cell population maintenance; cell population proliferation; lncRNA-mediated post-transcriptional gene silencing; mRNA destabilization; positive regulation of autophagosome size; positive regulation of autophagy; positive regulation of superoxide anion generation; post-transcriptional gene silencing; protein import into nucleus; regulation of mRNA stability; response to glucose
Cellular component: cytoplasm; cytosol; membrane; nucleolus; nucleoplasm; nucleus; cytoplasmic stress granule; ribonucleoprotein complex; cytoplasmic vesicle; endoplasmic reticulum; glutamatergic synapse; P-body; postsynapse
Genetic constraint (gnomAD): Loss-of-function variants: 1 observed, 30.01 expected, observed/expected ratio (o/e) 0.0333, 90% interval 0.011 to 0.16. The upper end of that interval is the gene's LOEUF score, 0.16, which puts it in group 1 of 6, group 1 being the genes least tolerant of losing a copy. Missense variants: 157 observed, 468.19 expected, observed/expected ratio (o/e) 0.34, 90% interval 0.29 to 0.38. Synonymous variants: 174 observed, 192.34 expected, observed/expected ratio (o/e) 0.9, 90% interval 0.8 to 1.03.
Homologues: Orthologues: chimpanzee ELAVL1 (100% identical), macaque ELAVL1 (100% identical), dog ELAVL1 (99% identical), rabbit ELAVL1 (99% identical), mouse Elavl1 (98% identical), pig ELAVL1 (98% identical), rat Elavl1 (98% identical), tropical clawed frog elavl1 (94% identical), zebrafish elavl1a (85% identical), guinea pig ELAVL1 (83% identical), zebrafish elavl1b (82% identical). Paralogues in human: ELAVL2 (74% identical), ELAVL4 (73% identical), ELAVL3 (69% identical), RBMS2 (27% identical), RBMS3 (27% identical), RBMS1 (25% identical), SF3B4 (25% identical), PABPC1 (25% identical), PABPC1L (25% identical), PABPC3 (24% identical), PUF60 (24% identical), SYNCRIP (23% identical), and 12 more.
Diseases named in the same sentence as ELAVL1 in open-access papers:
ELAVL1 is named in the same sentence as 319 diseases in open-access papers, as found by Europe PMC text mining. Sharing a sentence is not in itself a finding about the gene and the disease. The quoted sentences say what the papers report.
breast carcinoma (112 papers, 2010 to 2025). "ELAVL1 affects the development of breast cancer by regulating the mRNAs associated with a variety of proteins." (PMID 35465324, 2022). "Mechanistically, ELAVL1 promotes the expression of interleukin (IL)-8, which has clear connections with the progression of breast cancer, via binding to the 3′-UTR of the mRNA encoding IL-1β." (PMID 35465324, 2022). "Accordingly, among familial non-BRCA1/2 breast cancer patients, ELAVL1 can be used as an independent prognostic factor, associated with low survival rate and high tumor malignancy." (PMID 35465324, 2022). "Survival analysis found APP, TRIM25 and ELAVL1 to have significant associations with overall survival (log-rank p-value <0.05) in breast cancer." (PMID 34193143, 2021). "To confirm that HuR impacts GLS isoforms, both at the protein and mRNA levels, we knocked down ELAVL1 in 6 breast cancer cell lines (SKBR3, BT549, MDA-MB-231, MDA-MB-157, HCC38, and Hs578t)." (PMID 38965208, 2024). "In breast cancer cell lines, knocking down ELAVL1 changed the balance between KGA and GAC protein and mRNA levels, with a decrease in the first followed by a not-always proportional increase in the second." (PMID 38965208, 2024). "ELAVL1 silencing in breast cancer cells affected glutamine metabolism, leading to an increase in glutamine uptake, glutaminase activity, and glutamine dependence for growth." (PMID 38965208, 2024). "In this work, using The Cancer Genome Atlas (TCGA) database, we confirm that ELAVL1 is overexpressed in many cancers, including breast cancer." (PMID 38965208, 2024). "Cytoplasmic localization of ELAVL1 (embryonic lethal abnormal vision-like protein 1) and BRCA1 (breast cancer 1) gene mutations are associated with poor prognosis of breast cancer." (PMID 38378612, 2024). "We manipulate ELAVL1 expression levels in breast cancer cell lines and show that higher HuR levels correlate with increased KGA levels." (PMID 38965208, 2024). "A previous study demonstrated that ELAVL1 promotes breast cancer proliferation, metastasis, and chemoresistance." (PMID 36513874, 2023). "The clinical significance of MUC16 and ELAVL1 or Hu antigen R (HuR) was examined using breast cancer TCGA data." (PMID 36918912, 2023). "We have reported that HSF1 regulates β-catenin RNA, which contains many AU-rich sequences, in mammary cancer cells by controlling HuR/ElavL1 expression." (PMID 36982267, 2023). "Nevertheless, further studies are needed to clarify the reason that ELAVL1 is induced in breast cancer." (PMID 35346372, 2022). "In addition, another study demonstrated the cooperative function of ELAVL1/HuR in breast cancer cells in a manner distinct from that identified in other similar studies." (PMID 38689093, 2024). "Furthermore, we show that combining chemical inhibition of GLS with ELAVL1 silencing synergistically decreases breast cancer cell growth and invasion." (PMID 38965208, 2024). "Finally, we show that combining ELAVL1 silencing with glutaminase inhibition further impairs breast cancer cell growth, migration, and invasion." (PMID 38965208, 2024). "Overexpression of ELAVL1 is common in several cancers, including breast cancer." (PMID 38965208, 2024). "In breast cancer, increased ELAVL1 expression relates to a poor prognosis in patients." (PMID 38965208, 2024). "In breast cancer, miR-125a inhibited cell proliferation and promoted apoptosis by downregulating ELAVL1 which was highly expressed in cancer cells, and this effect was partially rescued by ELAVL1 overexpression." (PMID 35465324, 2022). "ELAVL1 is also regulated by upstream factors in breast cancer." (PMID 35465324, 2022). "ELAVL1 also plays an essential function in tumours such as colorectal cancer and breast cancer, suggesting that ELAVL1 may indeed serve as a potential marker for PAAD." (PMID 35711911, 2022).
breast carcinoma (continued). "In addition, the abnormal expression of cyclin E1, Wnt-5a, thrombospondin 1 and the colony stimulating factor receptor is directly related to the increased expression of ELAVL1 in breast cancer models." (PMID 35465324, 2022). "Silencing ELAVL1 inhibited breast cancer growth in vitro and in vivo." (PMID 30652415, 2019). "Silencing ELAVL1 inhibits breast cancer cell growth in vitro and in vivo." (PMID 30652415, 2019). "This study showed that FAM49B can activate the proliferation and metastasis of BC cells through the ELAVL1/Rab10/TLR4 pathway, and the malignant degree and aggressiveness of breast cancer with high expression of FAM49B were significantly increased." (PMID 34645466, 2021). "However, in our analysis using public databases, expression of the GM-CSF-encoding gene CSF2 was not strongly correlated with that of the HuR-encoding gene ELAVL1 in the different molecular subtypes of breast cancer." (PMID 28851919, 2017). "In addition, ELAVL1 expression showed a strong positive correlation with CCL20 expression but not with CSF2 or CCR6 expression in breast cancer subtypes, particularly the basal-like subtype." (PMID 28851919, 2017). "Experimental studies have shown that CDKN2A, PSAT1, HMGB1, ELAVL1, and SLC7A11 were up-regulated in TNBC, ASNS and LAMP2 were up-regulated in breast cancer and CAV1 was down-regulated in breast cancer, and HELLS was up-regulated in other tumors." (PMID 36568247, 2022). "Expression of the ELAVL1 (HuR) and ADRBK1 (GRK2) genes showed a direct correlation in breast cancer patients inspected with the web tool CANCERTOOL." (PMID 32413989, 2020). "In addition, both IGF2BP1 and ELAVL1 enhance the stability of MIR210HG, which contributes to the progression of breast cancer." (PMID 35346372, 2022). "We found that ELAVL1 was significantly overexpressed in 18 tumors (Kolgomorov-Smirnov FDR < 0.05), including breast cancer (BRCA), compared to normal controls; this difference was sustained in 16 tumors, including breast cancer (among others), when a paired normal: tumor comparison was made." (PMID 38965208, 2024). "In contrast with the findings for GM-CSF, ELAVL1 and CCL20 expressions were markedly increased in breast tumor tissues and ELAVL1 expression showed a strong positive correlation with CCL20 expression in breast cancer subtypes, particularly the basal-like subtype." (PMID 28851919, 2017). "In addition, the possible ferroptosis mechanisms of CDKN2A, PSAT1, SLC7A11, LAMP2, CAV1, and HMGB1 in TNBC and ASNS, ZFP69B, ELAVL1, TF, HELLS, and DPP4 in breast cancer have not been reported." (PMID 36568247, 2022).
gastric cancer (88 papers, 2013 to 2025). A primary or metastatic malignant neoplasm involving the stomach. "Elavl4 is considered a potential oncogene in glioblastoma because it stabilizes pro-survival mRNAs, while HuR (Elavl1) promotes tumour progression in hepatocellular carcinoma and gastric cancer, with its high cytoplasmic expression linked to poor prognosis." (PMID 40000387, 2025). "It has been established that ELAVL1 is up-regulated and associated with unfavorable outcomes in various cancer types, including lung cancer, ovarian cancer, pancreatic cancer, meningioma, esophageal squamous cell carcinoma, gastric cancer, and bladder cancer." (PMID 39815331, 2025). "In clinical gastric cancer cases, high levels of SNORA37, CMTR1, ELAVL1, or CD44 were associated with shorter survival and poor outcomes of patients." (PMID 39815331, 2025). "Linet al. reported that hypoxia-induced HIF-1α/lncRNA-PMAN inhibits ferroptosis by promoting the cytoplasmic translocation of ELAVL1 during peritoneal dissemination from gastric cancer." (PMID 40091620, 2025). "SNORA37, an ELAVL1-facilitated H/ACA box snoRNA derived from host gene MBD2, was up-regulated in gastric cancer tissues and associated with poor outcomes of patients." (PMID 39815331, 2025). "Western blotting assay showed that CMTR1 and ELAVL1 were up-regulated in human gastric cancer tissues than those in paired normal epithelia." (PMID 39815331, 2025). "Among them, ELAVL1, an essential splicing factor, was the only RBP associated with poor outcomes of gastric cancer." (PMID 39815331, 2025). "Hsa_circ_000613 binds to ELAV-like RNA-binding protein 1 (ELAV1, an RNA-binding protein, also known as HuR) to protect ELAV1 from ubiquitination and promotes the development of gastric cancer." (PMID 39090090, 2024). "ELAVL1/HuR was shown to promote gastric cancer cell proliferation in vitro and in vivo by negatively regulating miR-133b expression, in turn affecting the expression of the downstream gene CDC5L83." (PMID 38689093, 2024). "Studies showed that ELAVL1 promoted the progression of liver cancer, lung cancer, colorectal cancer, gastric cancer, esophageal cancer, breast cancer, prostate cancer, and ovarian cancer." (PMID 35945641, 2022). "Moreover, the decrease or increase in CD44v6 splicing, CD44v6/CD44s ratio, and CD44v6 expression in SNORA37 silencing or over-expressing gastric cancer cells were restored by transfecting expression vector or shRNA specific for CMTR1 or ELAVL1." (PMID 39815331, 2025). "However, the roles of ELAVL1 in regulating alternative splicing events in gastric cancer remain elusive." (PMID 39815331, 2025). "In addition, there was facilitated or reduced ELAVL1 enrichment on CD44 pre-mRNA in gastric cancer cells with stable over-expression or knockdown of CMTR1, while silencing or ectopic expression of SNORA37 abolished these effects." (PMID 39815331, 2025). "In this study, we identify SNORA37 as an ELAVL1-generated 129-nt H/ACA box snoRNA derived from host gene methyl-CpG binding domain protein 2 (MBD2), which is associated with progression and worse outcomes of gastric cancer." (PMID 39815331, 2025). "Accumulating evidence indicates that HIF-1α may be a potential driver of Hypoxia-induced HIF-1α/lncRNA-PMAN inhibits ferroptosis by promoting the cytoplasmic translocation of ELAVL1 in peritoneal dissemination from gastric cancer in gastric cancer." (PMID 39570876, 2024). "Cross-linking RIP assay revealed endogenous binding of ELAVL1 to intron 1 of MBD2 pre-mRNA in gastric cancer cell lines HGC-27 and AGS, which was attenuated by knockdown of ELAVL1." (PMID 39815331, 2025). "ELAVL1 stabilizes ZMYM1 mRNA in an m6A-dependent manner, enhancing gastric cancer progression by facilitating the transition from epithelial to mesenchymal tissue." (PMID 36348434, 2022). "In gastric cancer, m6A modifications are mediated by the CNV deletions of ELAVL1, YTHDF2 and FMR1, which then affects tumor formation." (PMID 33926554, 2021).
gastric cancer (continued). "SNORA37 directly binds to cap methyltransferase 1 (CMTR1) to facilitate its interaction with ELAVL1, resulting in nuclear retention and activity of ELAVL1 in regulating alternative splicing of CD44, which indicates the roles of SNORA37/CMTR1/ELAVL1 feedback loop in gastric cancer progression." (PMID 39815331, 2025). "Referring to studies of downstream targets regulated by METTL3 in tumours, it has been reported that in gastric cancer, METTL3 promotes ZMYM1 mRNA stability through m6A modification, subsequently enhancing its protein expression through the m6A reader protein HuR (also known as ELAVL1)." (PMID 38238831, 2024). "Moreover, silencing of ELAVL1 decreased the levels of SNORA37, without alteration of MBD2 expression, in gastric cancer cells." (PMID 39815331, 2025).
colorectal cancer (78 papers, 2009 to 2025). A primary or metastatic malignant neoplasm that affects the colon or rectum. "LncRNA OCC-1 exerted its function by binding to and destabilizing HuR (ELAVL1), which inhibited the cell cycle transition in colorectal cancer." (PMID 36527092, 2022). "ELAVL1 can promote the expression level of COX-2 in ovarian cancer as well as in colorectal cancer, and COX-2 is also positively correlated with poor prognosis and high-grade of ovarian cancer." (PMID 35465324, 2022). "For example, ELAVL1 positively regulates the cell division 6 protein, which is highly expressed in colorectal cancer and which drives both the malignant behavior of colorectal cancer and its resistance to oxaliplatin." (PMID 35465324, 2022). "Through targeting AREs in ELAVL1 mRNA, miR-155-5p negatively regulates the protein level of ELAVL1 and thus the migration of tumor cells in colorectal cancer." (PMID 35465324, 2022). "ELAVL1, also known as human antigen R (HuR), has been established as a tumor-specific antigen in colorectal carcinoma and tumors of the central nervous system." (PMID 35465324, 2022). "Our results highlight the crucial role of ELAVL1 in connecting inflammatory meditation with tumorigenesis, suggesting the potential role of ELAVL1 in carcinogenesis of colorectal cancer in the background of CD." (PMID 32724827, 2020). "The functions of ELAVL1 in colorectal cancer have been studied extensively." (PMID 35465324, 2022). "Interactions with the cell cycle also explain involvement of ELAVL1 in colorectal cancer." (PMID 35465324, 2022). "MiR-324-5p suppresses cell growth and invasion by regulating ELAVL1 in colorectal cancer." (PMID 32370736, 2020). "IGF2BP3, as an important RBP, has been reported to interact with ELAVL1 to recognize cell cycle and cell proliferation related genes, and lead to prolonged half-life of mRNA molecules and increased expression of target genes, thereby promoting colorectal cancer cell proliferation." (PMID 40083693, 2025). "RNA binding protein ELAVL1/HuR and NFKB, both of which appeared central in the network analysis, are suspected to work in concert with viral etiology on a background of predisposition circuitry to initiate and guide the pathogenesis of colorectal cancer in a subset of predisposed individuals." (PMID 26442106, 2015). "ELAVL1 (HuR), a homolog of ELAVL2, has recently been found to be significantly expressed in colorectal cancer and to have the ability to control the proliferation and migration of tumor cells." (PMID 38654363, 2024). "Second, ELAVL1 interacts with lncRNA OCC-1, which acts as a protective factor in colorectal cancer, inhibits the growth of tumor cells in vivo and in vitro." (PMID 35465324, 2022). "Importantly, studies have connected ELAVL1 to cyclooxygenase 2 (COX-2), which has been shown through in vivo and in vitro studies to be a key factor in the malignant progression of colorectal cancer." (PMID 35465324, 2022). "Moreover, the IGF2BP3/ELAV-like RNA binding protein 1 (ELAVL1) complex is involved in the stabilization of oncogenic transcripts, thus promoting tumorigenicity of colorectal cancer." (PMID 35677634, 2022).